IL6 (interleukin 6)
Diseases named in the same sentence as IL6 in open-access papers (continued):
Sharing a sentence is not in itself a finding about the gene and the disease.
pancreatic cancer (continued). "IL-6 is considered a biomarker for pancreatic cancer diagnosis and prognosis, as well as a potential target for treatment." (PMID 38828409, 2024). "It is conceivable that pancreatic cancer cells alter the host’s metabolism by secreting IL-6, and subsequently leverage the influence of hormones to bolster their defense." (PMID 38828409, 2024). "The results showed a sustained increase in levels of the mRNA expression of TNFα, IL-1β, and IL-6 in hypothalamic microglia, which started from the pre-cachexia stage and lasted for the cachexia stage after pancreatic cancer cell transplantation." (PMID 38685046, 2024). "TIM‐4 influences the differentiation of Treg by inhibiting IL‐6 secretion in pancreatic cancer cells and facilitates the proliferation of pancreatic cancer in mice." (PMID 39235042, 2024). "In the context of pancreatic cancer, autophagy facilitates the secretion of IL-6 from tumor cells, up-regulates FPN expression in CAF, leading to enhanced iron efflux, and subsequently increases the synthesis of LIP and ISC in tumor cells." (PMID 38853203, 2024). "This article aims to systematically explain how IL-6 induces the deterioration of normal pancreatic cells, with the goal of finding a breakthrough in pancreatic cancer diagnosis and treatment." (PMID 38828409, 2024). "Elevated levels of cytokines such as IFN-gamma, IL-6, IL-10, and TNF-alpha have been associated with an increased risk of pancreatic cancer." (PMID 39599705, 2024). "Research has demonstrated that IL-6, a multifunctional cytokine, is overexpressed in pancreatic cancer." (PMID 38828409, 2024). "Mediation analysis revealed that Interleukin-6 (IL-6), “CD4 on naive CD4+ T cell” and “SSC-A on HLA DR+ Natural Killer” mediated the causal effects of gut microbiota on pancreatic cancer." (PMID 39119339, 2024). "In any event, it can be determined that IL-6 acts as an inducer of cachexia in pancreatic cancer and suppressing IL-6 release represents a target for enhancing prognosis." (PMID 38828409, 2024). "Inflammatory cytokines like TNF-α, IL-1β and IL-6 were estimated in the spinal tissue of 5HT2A antagonist treated pancreatic cancer mice." (PMID 38629654, 2024). "Preclinical studies indicate that targeted IL-6 inhibition can enhance the efficacy of anti-PD-L1 therapy in pancreatic cancer." (PMID 38828409, 2024). "Using ELISA, it was found that the plasma IL-6 levels in untreated pancreatic cancer patients were significantly higher than those in healthy individuals, and IL-6 level were positively correlated with the tumor stage." (PMID 38828409, 2024). "IL-6 is elevated not only in serum but also in tumor tissues isolated from patients with pancreatic cancer." (PMID 36495330, 2023). "Researchers have confirmed that interleukin-6 (IL-6) increased the activation of AR in pancreatic cancer cells by upregulating the phosphorylation of signal transducer and activator of transcription 3 (STAT3) and mitogen-activated protein kinase (MAPK)." (PMID 36834922, 2023). "BA inhibits the proliferation, migration, and invasion of pancreatic cancer cells in vivo and in vitro through inhibiting IL-6 protein expression and AKT/STAT3 protein phosphorylation by mediating miR-365/BTG2 axis." (PMID 37415745, 2023). "Chronic inflammation induces IL-6 secretion from myeloid cells and pancreatic stellate cells, which promotes pancreatic cancer cell proliferation and invasiveness." (PMID 37814340, 2023). "Recent studies have shown that Raloxifene inhibits pancreatic cancer in vivo and in vitro via IL-6/gp130/STAT3 signaling." (PMID 37415745, 2023). "Within recent years, the cytokine interleukine-6 (IL-6) was recognized to promote the development and progression of pancreatic cancer." (PMID 36672405, 2023).
pancreatic cancer (continued). "IL-6 is elevated in patients with pancreatic cancer, suggesting this cytokine plays a role in blunting T cell immunity." (PMID 36881480, 2023). "Nab-PTX treatment increases CXCL-10 expression in pancreatic cancer cells leading to reduced secretion of CAF-derived IL-6 subsequently impairing cancer migration and invasion." (PMID 37480115, 2023). "IL-6 is elevated in the serum of pancreatic cancer patients and is assumed to play a key role in cachexia, advanced tumor stage and poor survival." (PMID 36672405, 2023). "As a result, the survival, proliferation, and glycolysis of pancreatic cancer cells can be dramatically decreased by inhibiting IL-6 and its related pathways, and the treatment resistance of pancreatic cancer cells can even be reduced." (PMID 37415745, 2023). "Currently, there is substantial evidence that the Notch signaling pathway regulates IL-6 levels in Graves’ ophthalmopathy, fibroblasts, endometriotic lesions and breast tumor cells of pancreatic cancer." (PMID 37449201, 2023). "al., analyzing peripheral blood from 73 pancreatic cancer patients explained that having a higher IL-6 level predicted a poorer overall survival." (PMID 37181043, 2023). "Mice bearing s.c. or orthotopic pancreatic tumors were treated with blocking Abs to IL‐6 and/or CTLA-4." (PMID 36881480, 2023). "Molecular targeting of the interleukin-6/glycoprotein-130/signal transducer and activator of transcription 3 signaling cascade is a promising approach in pancreatic cancer therapy." (PMID 36672405, 2023). "Clinically, in patients with pancreatic cancer, high serum levels of IL-6 correlate with poor prognosis, and Oncostatin M (OSM) was overexpressed in the sera of patients with PDAC." (PMID 36495330, 2023). "The only study that explored an increase in IL-6 level as one of the outcomes, was testing the function and safety of Pelareorep as a treatment for pancreatic cancer." (PMID 37181043, 2023). "The results showed some of the frequently cited inflammatory biomarkers for breast and pancreatic cancers included IL-6, IL-8, CCL2, CD8+ T cells and VEGF." (PMID 37181043, 2023). "For pancreatic cancer, after analyzing plasma IL6/IL8 levels in patients receiving chemoimmunotherapy, improved disease outcome was showed by treatment-induced IL6/IL8 decrease." (PMID 37181043, 2023). "IL6 upregulation has also been correlated with upregulation of NRP1 in pancreatic cancer cells suggesting their mutual involvement with pro-inflammatory pathways and cancer development." (PMID 37953774, 2023). "Experiments performed on a mouse model of pancreatic cancer and cell lines proved both molecules to enhance low-dose paclitaxel effects by increasing apoptosis in tumor cells or reducing interleukin-6 levels, respectively." (PMID 36672405, 2023). "IL-6 levels returned to baseline levels at 72 h post-infusion, except for in one patient with pancreatic cancer in the 2.0 mg/kg cohort in which IL-6 levels remained elevated until C1D15." (PMID 36991390, 2023). "IL-6, as a proinflammatory cytokine, plays a pivotal role in tumor progression, including breast, lung, ovarian, colorectal, and pancreatic cancer." (PMID 37821959, 2023). "IL-6 is a key immune response factor, and the activity of pancreatic cancer cells can be stimulated by IL-6, which can also encourage cell growth, EMT, and immune evasion of tumor cells." (PMID 37415745, 2023). "The frequency of RAS mutations in pancreatic carcinoma is high; therefore, although many SASP were found in PAAD, we chose IL-1α and IL-6 for further analysis." (PMID 36622275, 2023). "IL-6 also induces a mesenchymal phenotype in human pancreatic cancer cells via STAT3 activation and SNAI1 induction." (PMID 36010693, 2022). "Parallel with these findings, we also found significantly increased pro-inflammatory cytokine IL-6 and IL-8 from pancreatic cancer patients compared to control, indicating the high probability of an activated NFkB pathway in these patients." (PMID 35269689, 2022).
pancreatic cancer (continued). "Relevant studies have shown that REG3A acts as a growth-promoting cell regulator and interacts with JAK2/STAT3 signaling to form a positive feedback loop to accelerate pancreatic cancer cell growth under IL-6-related inflammatory conditions." (PMID 36105933, 2022). "We found significantly increased IL-8 and IL-6 cytokine levels in the plasma of pancreatic cancer patients compared to the healthy control group (p < 0.01 and p < 0.0001, respectively)." (PMID 35269689, 2022). "We found significantly higher levels of both IL-6 and IL-8 cytokines in colorectal (p = 0.0001 and p = 0.0119, respectively) and pancreatic cancer patients (p < 0.0001 and p = 0.0043, respectively) compared to controls." (PMID 36139592, 2022). "Impressively, it has been gradually elucidated that IL6 secreted by CAFs mediates immunosuppression in pancreatic cancer." (PMID 35189958, 2022). "In fact, Ras-driven pancreatic tumors are described to promote IL-6 secretion leading to STAT3 signaling pathway activation." (PMID 35159208, 2022). "In pancreatic cancer, KRAS mutations are present in the majority of the cases, as are high levels of IL-6." (PMID 35159208, 2022). "IL1ɑ secreted by pancreatic tumor cells and subsequent IL6/JAK/STAT3 activation in CAFs have been shown to trigger iCAF formation." (PMID 36109493, 2022). "We analyzed genetic data from pancreatic cancer and found that IL-6 expression was much higher in PAAD than in normal pancreatic tissue." (PMID 36105933, 2022). "IL-6 is a proinflammatory cytokine produced by various cells including pancreatic cancer cells, hepatocytes and macrophages." (PMID 35493517, 2022). "Studies in pancreatic cancer models have demonstrated that inflammatory moieties such as TGF-β and IL-6 are implicated in the process of metastasis." (PMID 35740519, 2022). "IL-1β, IL-6, IL-8, IL-10, TGF, and VEGF are PDAC-associated cytokines studied in duplicate in more than four studies, and are elevated in pancreatic cancer." (PMID 35159120, 2022). "As a major member of the tumor inflammatory microenvironment, the proinflammatory cytokine IL-6 is involved in the development and progression of pancreatic cancer." (PMID 36105933, 2022). "Combination of IL‐6 inhibitor with PD‐L1 blockade therapy increases T cell infiltration and enhances OS in mice with pancreatic cancer." (PMID 35301813, 2022). "In a murine model of pancreatic cancer, inhibition of IL6 in combination with inhibition of PD-L1 resulted in increased infiltration of effector CD8+ T-cells into tumours and impaired tumour growth." (PMID 36138073, 2022). "IL6 overexpression has also been reported to promote Th17 differentiation of CD4+ T-cells with anti-tumour activity in a transplantable murine model of pancreatic cancer." (PMID 36138073, 2022). "Our results showed that various inflammatory cytokines, such as IL-1β, IL-6, IL-8, and IL-15, were more expressed in pancreatic cancer than in the matching normal tissue." (PMID 35630552, 2022). "Benzyl isothiocyanate-induced decreases in the levels of phosphorylated and total STAT3, a downstream effector of IL-6, were shown to promote apoptosis in pancreatic cancer cells." (PMID 36551971, 2022). "Human pancreatic cancer cells were shown to utilize IL‐6‐mediated Jak2‐STAT3 signaling to form a trimeric complex of Cdc42 with its interaction partner IQGAP1 and STAT3 for IQGAP‐mediated activation of Cdc42." (PMID 33960104, 2022). "IL-6 was reported to inhibit radiation-induced apoptosis and promote survival in pancreatic cancer cells by upregulating Bcl-XL." (PMID 36551971, 2022). "As circCUL2 contributes to iCAF phenotype development and the enrichment of the cytokine IL6 in pancreatic cancer, further exploration is needed to reveal its role in the immunosuppression of pancreatic cancer." (PMID 35189958, 2022).
pancreatic cancer (continued). "As we also found significantly increased levels of IL-8 and IL-6 cytokine in the plasma of pancreatic cancer patients, we suppose this was probably through IL17/NFkB/STAT3 signaling." (PMID 35269689, 2022). "This study revealed that IL-6, IL-1beta, and other inflammatory factors are highly expressed in samples from pancreatic cancer patients compared with the corresponding matching normal tissue, and this result is consistent with previous findings." (PMID 35630552, 2022). "In another study in murine models of pancreatic cancer, the blockade of IL-6 using an antibody enhances the antitumor efficiency of anti-PD-L1 antibodies." (PMID 35444660, 2022). "We collected 35 serum samples from pancreatic cancer patients and measured IL-8 and IL-6 pro-inflammatory cytokine levels in their plasma by ELISA." (PMID 35269689, 2022). "First, we found miR-301a was induced in both human and mouse PSCs after TGF-β or IL-6 treatment as well as in mouse embryonic fibroblast and pancreatic cancer cells." (PMID 35211358, 2022). "Epithelial Stat3 ablation attenuated fibrosis and tumor progression in Smad4 mutant pancreatic tumors in mice, and several studies demonstrated that blockage of the IL-6/Stat3 axis suppresses Kras-induced pancreatic adenocarcinoma." (PMID 35211358, 2022). "IL-6 has also been demonstrated to act through the MAPK pathway in pancreatic cancer cells, thereby promoting cell survival." (PMID 36551971, 2022). "A human pancreatic cancer (PC) cell, Capan‐1, was confirmed to have the stimulant activity of IL‐6/gp130 axis through the evaluation of mRNA, cell surface protein and intracellular protein levels and chemotaxis and wound healing assay." (PMID 35578571, 2022). "For example, interleukin-6 secreted from PSCs promotes cell proliferation, stemness, and drug resistance of pancreatic cancer cells." (PMID 36012531, 2022). "Cancer cell-induced lipolysis in adipocytes was stimulated using cancer-conditioned media (CCM) or co-culture with human pancreatic cancer cells and the cachexia-associated cytokines TNF-α and interleukin-6 in 3T3-L1 adipocytes." (PMID 35684106, 2022). "This pathway has been found to be active in pancreatic cancer and bazedoxifene has been proposed as part of the treatment as it seems to downregulate the IL6/PG130/STAT3 pathway." (PMID 35626089, 2022). "In contrast, inhibition of the IL-6 signaling pathway significantly reduces primary tumor growth and recurrence in an orthotopic xenograft pancreatic cancer model." (PMID 36105933, 2022). "Mesothelin overexpression in pancreatic cancer cells leads to the constitutive activation of NF-κB, thereby increasing the production of IL-6 and enhanced tumor cell proliferation and survival via auto/paracrine IL-6/sIL-6R trans-signaling." (PMID 35326701, 2022). "A previous study showed that interleukin-6 (IL-6) inhibits hepatic albumin production in patients with pancreatic cancer and is positively correlated with serum CRP levels." (PMID 35795140, 2022). "In this study, we show that FAK expressed in kras mutant murine pancreatic cancer cells regulates the expression of IL6, which acts to amplify IL4-dependent expression of the immune checkpoint ligand PD-L2 within the PDAC TME." (PMID 36138073, 2022). "In several studies, anti-IL-6 blocking antibodies or sGP130Fc has been demonstrated to inhibit IL-6 signaling and induce apoptosis in breast and pancreatic cancer cells and animal models." (PMID 34445405, 2021). "Previous studies have shown that “basal” IL-6 released from PSCs plays a leading role in activating the JAK/STAT3 pathway in pancreatic cancer cells." (PMID 34440697, 2021). "IL6 trans-signaling promotes pancreatic intraepithelial neoplasia to progress to pancreatic cancer and drives niche formation in liver metastasis." (PMID 34276760, 2021). "In turn, IL-6 released from PSCs stimulates STAT3 activation in pancreatic cancer cells, indicating that the P2X7R is an important factor in the PSC-cancer cell crosstalk." (PMID 34440697, 2021).
pancreatic cancer (continued). "Proinflammatory cytokine Interleukin-6 (IL6) is often upregulated in pancreatic cancer and is required for cancer progression in vivo." (PMID 34439095, 2021). "The combination of anti-IL-6 and anti-PD-L1 therapy effectively increases the survival rates of pancreatic cancer mice." (PMID 34988078, 2021). "Combined blockade of IL-6 and PD-L1 in mice models of pancreatic cancer led to attenuated tumor growth, prolonged survival, and increased infiltration of T cells." (PMID 34203869, 2021). "Siltuximab (CNTO 328) is another mAb directly targeting the IL-6, evaluated in monotherapy in a phase I/II study in patients with solid tumors including pancreatic neoplasms." (PMID 34451837, 2021). "IL6 is a potent proinflammatory cytokine which is elevated in patients with pancreatic cancer and potentially increases tumor cell invasion in vitro." (PMID 35154607, 2021). "We found these methylation-predicted CRP Scores to be moderately correlated with log-CRP and log-IL6 in the controls of a previously published pancreatic cancer dataset." (PMID 34915912, 2021). "Despite the success of blocking IL-6 in pancreatic cancer animal models, this approach was virtually ineffective in a clinical setting." (PMID 34988078, 2021). "AKT1, CDKN2A, ERBB2, and IL6 are common protein core of liver and pancreatic cancers, while STAT3, CASP3, NOTCH1, and CTNNB1 are possible differential proteins to discriminate these cancers." (PMID 35154607, 2021). "For example, IL6 secreted from Th2 cells plays a critical role in promoting pancreatic cancer development." (PMID 34777634, 2021). "So far, we discussed the evidence that P2X7R stimulation of PSCs causes the release of IL-6, which stimulates STAT3 signaling in pancreatic cancer cells." (PMID 34440697, 2021). "The current findings indicate that AKT1, CDKN2A, ERBB2, and IL6 are the critical common hubs related to promoting both liver and pancreatic cancers." (PMID 35154607, 2021). "In contrast, the inhibition of IL6 signaling reduces pancreatic cancer growth and recurrence in xenograft models." (PMID 34276760, 2021). "This cascade results in the upregulation of other proinflammatory cytokines, such as interleukin-6 (IL-6) which affect the progression of the pancreatic cancer." (PMID 34884547, 2021). "This led to inhibited STAT3 phosphorylation and suppressed growth of pancreatic cancer cells with intact IL-6/gp130 signaling in both in vitro and in vivo settings." (PMID 34149710, 2021). "IL-6/STAT3 signaling can promote pancreatic cancer growth and metastasis, which induce suppressor of cytokine signaling 3 (SOCS3) methylation through DNA methyltransferase 1 (DNMT1)." (PMID 33406733, 2021). "MUC16c participates in the regulation of Treg differentiation by promoting the expression and secretion of IL-6, which promotes the immune escape of pancreatic cancer." (PMID 34490033, 2021). "The CD95L-antagonist sCD95Fc substantially reduced cytokine (TNF-α or TRAIL)-stimulated IL-6 and IL-8 expression and generally lowered the pro-inflammatory status of pancreatic cancer cells as well as their stem cell properties." (PMID 34771621, 2021). "The current results indicate that AKT1, CDKN2A, ERBB2, and IL6 are the common protein core of liver and pancreatic cancers, and STAT3, CASP3, NOTCH1, and CTNNB1 are possible differential proteins that discriminate these cancers." (PMID 35154607, 2021). "Lee and colleagues investigated the role of IL-6 in forming the pre-metastatic niche in the liver in mouse models of pancreatic cancer." (PMID 33322216, 2020).